IL15 (interleukin 15)
Diseases named in the same sentence as IL15 in open-access papers (continued):
Sharing a sentence is not in itself a finding about the gene and the disease.
tumor (continued). "We present a bicistronic retroviral vector encoding both a tumor vasculature–targeted CAR and murine interleukin-15 (mIL-15), conferring enhanced effector functions, engraftment, tumor control, and TME reprogramming, including NK cell activation and reduced presence of M2 macrophages." (PMID 33156338, 2021). "Thus, genetic engineering of NK cells, and in particular CAR-NK cells to express IL-15 can enhance the persistence and cytotoxicity against tumor cells." (PMID 33946954, 2021). "Nevertheless, these studies focused on the microenvironment of the tumor itself, suggesting that IL-15 expression, when found in the microenvironment, may provide a benefit for patients." (PMID 32929618, 2021). "It is hypothesized that IL-15 promotes tumor progression via induction of survival and anti-apoptotic signals in malignant T-cells, while IL-32 has been shown to accelerate the proliferation of CTCL cell lines through MAPK and NF-KB dependent mechanisms." (PMID 34204115, 2021). "Others have reported superior tumor control by IL-7/IL-15 than IL-2–expanded T cells." (PMID 33156338, 2021). "T-cell stimulatory common γ chain cytokines IL-7, IL-15, or IL-21 are capable of supporting the generation of memory cells with improved mitochondrial fitness and less overt T-cell differentiation compared to the use of IL-2, improving anti-tumour immunity." (PMID 34960140, 2021). "Based on these findings, we hypothesized that increased PD-L1 expression detected in BC patients with low circulating IL-15 level is a consequence of attenuated anti-tumour response proposed by Jabrie and Abadie34." (PMID 33446741, 2021). "The independent activity of both IL-15 fusions and 4-1BB agonists has been demonstrated for in vivo tumor inhibition; however, there is a clear benefit for the simultaneous presentation of IL-15 and 4-1BBL in a single fusion protein in a tumor mouse model in vivo." (PMID 34244816, 2021). "We discovered that CAR-T cells expanded with IL-15 had reduced dysfunction and enhanced persistence compared to those grown with IL-2 or a combination of IL-15 and IL-7, which resulted in longer and improved anti-tumor responses in a mouse model." (PMID 34298748, 2021). "However, in vitro cultured tumor-infiltrating NK cells with IL-15 overcome resistances and restore NK cell function and anti-tumor activity in HCC." (PMID 34445750, 2021). "Interestingly oncolytic adenovirus armed with CCL5 and IL-15 enhanced CAR-T recruitment to tumour sites and cytotoxicity in an in vivo model of neuroblastoma." (PMID 34888493, 2021). "Therefore, the stability of IL-15/IL-15Rα complex is essential for IL-15 to perform tumor immune function." (PMID 34386015, 2021). "Analysis of early lesions revealed that IL15 stimulates two separate populations of T cells, as well as natural killer and dendritic cells to target cancerous growth, thus highlighting it as a key tumor suppressive cytokine." (PMID 33235291, 2021). "In addition, IL-15 induced higher toxicity in BrHPP activated Vγ9Vδ2 T cells against different adherent tumor cells compared to IL-2." (PMID 32456316, 2020). "To examine whether the observed superiority of IL-2/IL-15-expanded Vγ9Vδ2 T cells persists in conditions more resembling those of the tumor microenvironment, we repeated the cytotoxicity assays against ZOL-pre-treated FM-28 cells in hypoxia (1% O2)." (PMID 32983105, 2020). "We described that CTLA-4 might regulate tumor immune microenvironment by enhancing relevant immunomodulators, such as IL-15 and CSF-1, which prime NK and M1 macrophages, two cells interconnected by their immunomodulatory functions." (PMID 32850353, 2020). "Alternatively, TCR therapy could be combined with additives that protect both T and NK cells from tumour mediated immunosuppression such as immune checkpoint inhibitors (e.g., anti-PD-1 antibodies) or cytokines (e.g., IL-15)." (PMID 32183246, 2020). "The incorporated IL-15 dramatically increased anti-tumor activity in the CD19-CAR NK cells." (PMID 33287875, 2020).
tumor (continued). "Interestingly, it has been recently shown that cord blood-derived NK cells expressing CD19 and the suicide gene inducible Caspase-9 (iC9) and producing IL-15 (CAR CD19/IL-15/iC9) exhibited an efficient killing of CD19+ tumor B cells both in vitro and in vivo." (PMID 32610578, 2020). "In the TME, it must be considered that while IL-15 may be upregulated due to the chronic inflammatory nature of tumor formation, other suppressive mechanisms can override robust IL-15 signaling in NK cells under these circumstances." (PMID 32082327, 2020). "Here, we hypothesized that IL-15 administration with cancer cell-targeted NIR-PIT could further inhibit tumor growth by increasing antitumor host immunity." (PMID 32927646, 2020). "Therefore, CD16-directed bispecific (eg, CD16 and CD19) or trispecific (eg, CD16 and two tumor antigens CD19 and CD22 or one tumor antigen and an IL-15 linker) antibodies or scFv have been developed." (PMID 32273348, 2020). "Importantly, a significant antitumor activity including long-term complete tumor regression has been shown in animals treated with intratumoral delivery of IL-15/IL-15Rα co-expressing DNA." (PMID 33628206, 2020). "Moreover, oncolytic viruses that express IL-15 significantly lyse tumor cells and reduce the tumor volume by activating natural killer (NK) cells, CD8+ T cells, and other immune cells." (PMID 32587256, 2020). "We conclude that Cish regulates IL-15 signaling in NK cells in vivo, and through the rewiring of several activation pathways leads to a reduction in activation threshold, decreasing the requirement for priming and improving NK cell anti-tumor function." (PMID 32082327, 2020). "Also, in this less TCR-dependent manner of tumor recognition, IL-2/IL-15-expanded cells performed better than IL-2-expanded cells." (PMID 32983105, 2020). "Similarly, IL-15 in combination with IL-2, boosted the proliferation as well as the in vitro anti-tumor activity of ZOL-expanded Vγ9Vδ2 T cells." (PMID 32456316, 2020). "Moreover, elimination of MDSCs with PD-L1-directed CAR-NK cells was a highly effective therapy in a MOC1 murine tumor model when combined with an anti-PD-1 antibody and the IL-15 super-agonist N-803." (PMID 33120910, 2020). "Administration of exogenous IL-15 suppressed tumor growth in various preclinical models." (PMID 33266177, 2020). "As an example for the application of CRISPR in oncolytic virotherapy, CRISPR-Cas9 has been used to construct IL-15-expressing herpes simplex virus II, which showed potential in increasing the anti-tumor activity of T-cells and suppressing tumor growth in colon and gastric cancer models." (PMID 32973401, 2020). "For instance, administration of IL-15 which has been shown to boost anti-tumor immunity in vitro." (PMID 33194687, 2020). "That Cish-deficient NK cells still show significant death in low concentrations of IL-15 combined with the similar anti-tumor response observed in DKO mice suggests that increased survival is not a factor contributing to the anti-tumor function of Cish-deficient NK cells in vivo." (PMID 32082327, 2020). "However, it needs to be stressed that ROS severely impair NK-cell activity and survival, as IL-15-primed NK-cells upregulate thioredoxin activity to protect themselves from cytotoxic ROS in the tumor microenvironment (TME)." (PMID 33265951, 2020). "While NK cells positively promote DC infiltration and maturation via release of pro-inflammatory cytokines such as interferon (IFN)-γ, myeloid-derived cytokines, including interleukin (IL)-12, IL-15, and IL-18, critically promote NK cell maturation, proliferation, and anti-tumor functions." (PMID 33584718, 2020). "Here we discuss the distinct roles of IL-2 and IL-15 in activating various functions of T and NK cells with a particular focus on the signals that contribute to the resistance of immune suppressive factors within the tumor microenvironment." (PMID 33266177, 2020).
tumor (continued). "We showed in the TRAMP-C2 murine syngeneic tumor model that treatment with either an agonistic anti-CD40 antibody alone or IL-15 prolonged animal survival, however the combination of agonistic anti-CD40 with IL-15 produced markedly additive effects when compared with either agent alone." (PMID 32508818, 2020). "We hypothesized that IL-15 administration following cancer-antigen targeted NIR-PIT could enhance tumor growth inhibition." (PMID 32927646, 2020). "An additional possibility is that excised tumors of patients could be confronted with ex vivo–expanded autologous NK cells and exogenous cytokines IL-15, IL-18, IL-22, and IL-23 to reactivate the immune response and establish specific tumor recognition." (PMID 33276556, 2020). "A second immunotherapy approach consists of tumor extirpation to infiltrate it later with Th1 cells and IL-15, IL-18, and IFN-α cytokines and subsequently reimplant the tumor-tissue into the patient, in a subcutaneous region closer to some lymph nodes intraperitoneal." (PMID 33276556, 2020). "Chemotherapy with cyclophosphamide and fludarabine is used for elimination of immunosuppressive cells such as Tregs, as well as for elimination of endogenous non-tumour-specific T cells that compete with therapeutic cells for interactions with APCs and activating cytokines, such as IL-7 and IL-15." (PMID 32183246, 2020). "However, tumor growth can also be inhibited by the injection of proinflammatory cytokine interleukin-15 into adipose tissue via recruitment of natural killer cells to inhibit tumor metastasis." (PMID 32471255, 2020). "For all donors, IL‐15‐activated NK cells killed tumour cells in preference to the NP cells." (PMID 31784984, 2020). "However, tumor-bearing mice receiving the combination of both anti-checkpoint antibodies with IL-15 manifested a significant prolongation of survival." (PMID 32508818, 2020). "Similarly to IL-2, there have been various analogs of IL-15 developed to increase the anti-tumor efficacy and lower the toxicity." (PMID 31179236, 2019). "Moreover, ALT-803 has been used as a functional scaffold for creating multispecific, targeted IL-15-based immunotherapeutic agents to enhance tumor clearance." (PMID 31623224, 2019). "Moreover, increased IL-15 gene expression in the tumor microenvironment correlates with improved survival of colorectal cancer patients." (PMID 30863720, 2019). "We demonstrated that FmIL-15 is expressed by infected murine tumor cells and that the secreted fusion protein is functionally active, as shown by its ability to promote survival and to induce the expression of IL-15 target genes in cytokine-dependent lymphocytes in vitro." (PMID 31623390, 2019). "However, IL-15 together with autologous TILs induced an immune-mediated destruction of tumor spheroids compared to control condition or IL-15 alone, showing that TILs stimulation can exert antitumor effect in these autologous conditions." (PMID 30871626, 2019). "Stimulation of DNTs with IL-15 further enhances their anti-tumor activities." (PMID 30670085, 2019). "Therefore, we incorporated CD28 costimulation and IL-15 culture into our in vitro differentiation model to generate memory phenotype OT-1 T cells for ACT to EL4-OVA tumor-bearing mice." (PMID 31335326, 2019). "The splenic eosinophils in cryo-thermal-treated mice expressed high level of chemokines and pro-inflammatory cytokines (CCL5, CXCL10, IFN-γ, IL-6, IL-12 and IL-15), which could create immunostimulatory microenvironment contributing to anti-tumour immunity." (PMID 31519961, 2019). "Moreover, anti-CTLA-4 combined with IL-15/IL-15Rα enhances the NK cell tumor infiltration, improving the tumor growth control in xenograft murine models of solid tumors." (PMID 32038612, 2019). "The anti-tumor effect of DNTs is achieved by utilizing various mechanisms that depend on the presence of tumor ligands, and those mechanisms can be enhanced by the addition of IL-15." (PMID 30670085, 2019).
tumor (continued). "The TILs were then stimulated with the PanTT26 tumour cell line (autologous) three times to see whether repeated exposure of the IL-2/IL-15/IL-21-conditioned TILs to the tumour would lead to enrichment of tumour epitope-reactive T cells." (PMID 30377343, 2019). "However, IL-15 increased tumor cell apoptosis induced by the combination of CD4 and CD8 T cells, implying that IL-15 is not exclusively sensed and active through NK cells." (PMID 30871626, 2019). "However, a recent study showed that continuous IL-15 signaling impairs NK cell anti-tumor activity through a metabolic defect." (PMID 31340613, 2019). "IL-15-stimulated NK cells showed a faster degranulation response in vivo than IL-12/15/18 that may account for their higher capacity to restrain tumor burden within a short time-frame (48 h)." (PMID 31699153, 2019). "Moreover, we discuss the potential of IL-15 and its analogs and IL-12 cytokines in combination with RT based on the efficacy in preclinical mouse tumor models." (PMID 31179236, 2019). "Accumulating evidence shows that IL-15 agents have some efficacy as monotherapy, but they have a great potential when used in combination with chemotherapy agents, resulting in enhanced NK cell activity against tumor recurrence and metastasis in animal models." (PMID 30867508, 2019). "Therefore, there is increasing attention on strategies combining IL-15 and NK immunotherapy to maximize anti-tumor effects and limit NK hyporesponsive following adoptive transfer." (PMID 30646520, 2019). "Similar results were obtained when IL-15/IL-15rα was substituted for IL-12P70, demonstrating the robustness and transposability of our approach to express proteins of therapeutic interest in a tumor cell-dependent manner." (PMID 31723132, 2019). "IL-2 and IL-15 represent the first molecules used to induce the proliferation and increase the cytotoxic potential of both T and NK cells for adoptive cell transfer therapies in different tumor settings." (PMID 31849972, 2019). "Additionally, IL-15 is able to reverse tumor-tolerant CD8+ T cells, when IL-2 and IL-7 were unable to, restoring antigen responsiveness and leading to tumor clearance." (PMID 30842774, 2019). "Dual blockade of IL-2 and IL-15 abrogated the IL-1β enhancement of ACT-mediated tumor regression." (PMID 31405895, 2019). "In this study, IL-15 modified CD19 CAR T cells secreted IL15 following antigen stimulation, showed enhanced survival as a result of the transgenic cytokine, expanded better in vivo, and have better in vivo anti-tumor activity." (PMID 31024832, 2019). "By performing competitive homing experiments in tumor-bearing mice, we demonstrated that Cxcr3−/− deficiency promoted increased BM infiltration for IL-15 activated but not IL12/15/18 activated Cxcr3−/− NK cells compared to the wild-type counterparts." (PMID 31699153, 2019). "Suppressive effects of TGF-β may also be overcome by targeted delivery of cytokines IL-2, IL-15, and IL-18 into the tumor." (PMID 31803194, 2019). "Other clinical studies have been designed to test the ability of IL-15 to increase antibody-dependent cellular cytotoxicity (ADCC) effects, using IL-15 in combination with tumour-targeting monoclonal antibodies such as alemtuzumab (NCT02689453) or rituximab (NCT02384954)." (PMID 30413827, 2019). "Interestingly strong trends towards increased plasma levels of cytokines and chemokines associated with protective anti-tumor immunity was also evident including: IL-1b, IL-12, MIP1a, MIP1b, MCP-1, IL-15, IFNγ, IFNα, IL-1R, IP-10, MIG, IL-8." (PMID 31426803, 2019). "We hypothesized that MeVac equipped with an IL-15/IL-15R fusion protein may have enhanced immunotherapeutic efficacy by stimulating anti-tumor CD8+ effector T cell and NK cell responses." (PMID 31623390, 2019).
tumor (continued). "Cytokines of the common γ-chain receptor family such as IL-15 are vital with respect to activating immune cells, sustaining healthy immune functions, and augmenting the anti-tumor activity of effector cells, making them ideal candidates for cancer immunotherapy." (PMID 31856922, 2019). "In addition, in vivo assay also revealed elevated IL-15 levels in tumor tissues after infecting with SG400-E2F/IL-15." (PMID 31278126, 2019). "Moreover, many of the factors de-repressed upon MITF knockdown are important players that activate anti-tumor immunity (e.g. IL15, CCL2), which suggests a potential role of MITF in evasion of immune surveillance." (PMID 31554806, 2019). "Furthermore, SG400-E2F/IL-15 injection triggered cell rupture in E2F1-positive tumor cells as well as a large amount of tissue necrosis." (PMID 31278126, 2019). "Meanwhile, tumor immune-related pathways were also enriched, such as B cell development pathway, cd28 signaling in T Helper cell, chemokine signaling, IL-1 signaling, IL15 signaling, IL-2 signaling, IL-3 signaling, IL-4 signaling, and IL-8 signaling." (PMID 31258820, 2019). "We performed multiplex immuno-assay (Luminex) to assess the presence of inflammatory cytokines involved in the regulation NK cells function, such as TNF-α, IFN-γ, IL-6, IL-15, and IL-1β, in the tumor microenvironment (black bars) and in the healthy adjacent tissue microenvironment (white bars)." (PMID 31105699, 2019). "Moreover, IL-2 and IL-15 stimulation of NK cells enhanced Avelumab-triggered cytokine production and degranulation along with increased lytic activity against tumor cells." (PMID 30294328, 2018). "Moreover, the anti-tumor effect of IL-15 on the immune system has been well-documented in experimental systems." (PMID 29692776, 2018). "In conclusion, co-expression of the stimulatory cytokine IL-15 enhanced the NB-specific anti-tumor effectivity of a TH-directed vaccination in mice and may provide a novel immunological approach for NB patients." (PMID 30452438, 2018). "NK cells briefly pre-activated by this combination of cytokines (IL-12, IL-15 and IL-18) were previously shown to have a sustained effector function in tumour mouse models and an enhanced proliferative capacity as well as an increased IFN-γ response over time in human in vitro studies." (PMID 29433450, 2018). "After establishing the stimulatory effect of IL-15 DCs on γδ T cell proliferation and pro-inflammatory cytokine production, we looked at their ability to improve γδ T cell lysis of a panel of leukemic tumor cell lines and primary AML blasts." (PMID 29692776, 2018). "Our example of ex vivo tumor-infiltrating NK cells being re-activated by IL-15 suggests that direct delivery could be used in liver tumors to activate local NK cells in vivo while minimizing systemic toxicity." (PMID 29867983, 2018). "Moreover, IL-15 fused with the extracellular domain of NKG2D (dsNKG2D–IL-15) exhibited enhanced NK cell tumor infiltration and higher efficiency than IL-15 in suppressing xenografted GC growth in nude mice." (PMID 30719024, 2018). "Using iterative rounds of in vivo screening in murine syngeneic tumor models, a mixture of four synthetic mRNAs encoding bioactive versions of interleukin-12, interferon alpha, GM-CSF and interleukin-15 was identified which mediated complete tumor regression across multiple different tumor models." (PMID 30400822, 2018). "Moreover, in tumor-free animals only dual-switch/IL-15 NK cells with weekly rimiducid stimulation expanded and persisted in vivo (up to 7 weeks)." (PMID 30400835, 2018). "Importantly, CIS serves as a novel checkpoint in NK cell-mediated anti-tumor responses by targeting IL-15 signaling." (PMID 30250471, 2018). "Additionally, we aimed to enhance anti-tumor responses by co-administration of the immune stimulatory cytokines IL-15." (PMID 30452438, 2018).